SNAI2 (snail family transcriptional repressor 2)
Diseases named in the same sentence as SNAI2 in open-access papers (continued):
Sharing a sentence is not in itself a finding about the gene and the disease.
cancer (417 papers, 2007 to 2026). A tumor composed of atypical neoplastic, often pleomorphic cells that invade other tissues. "Results from OS, DSS, DFI, and PFI analyses were highly consistent, showing that SNAI2 is significantly associated with the prognosis of cancer patients." (PMID 37251370, 2023). "In this paper, pan-cancer samples from public databases were included for subsequent analysis including expression differences, the landscape of SNAI2 mutations, the correlation between expression and survival, and immune infiltration." (PMID 37251370, 2023). "Overexpression of SNAI2 is a common occurrence in human tumors, and it is associated with a bad prognosis in cancer patients." (PMID 37251370, 2023). "Although critical in normal development and wound healing, aberrant EMT has been linked to cancer metastasis, and over-expression of EMT drivers, such as SNAI1 and SNAI2, are associated with poor clinical prognoses in cancer." (PMID 33557266, 2021). "Slug is encoded by Snail zinc finger family 2 (SNAI2) and is found to be overexpressed in human cancers in association with poor prognosis in clinical studies." (PMID 32987716, 2020). "As a member of the SNAI/SLUG superfamily, SNAI2 has been implicated in the pathogenesis of different cancers." (PMID 29552304, 2018). "The top five up-regulated cancer stemness associated genes include: SNAI2 (SLUG) (8.2 folds), SOX9 (6.4 folds), ITGB3 (integrin β3) (5.4 folds), CD44 (4.3 folds) and MET (2.9 folds) (DU145FP vs. DU145WT)." (PMID 28698547, 2017). "This resulted in an increased expression of SNAI2, encoding the Snail zinc finger protein Snai2 that is involved in cancer invasion and metastasis." (PMID 27275536, 2016). "Overexpression of SNAI2/SLUG can be observed in a variety of different cancers and seems to be associated with poor outcome." (PMID 25928859, 2015). "Aberrant expression of SNAI1 and SNAI2 is also linked to cancer metastasis in epithelial cell lines through its role in directing epithelial-to-mesenchymal cell transition (EMT)." (PMID 20046880, 2009). "TWIST1 and SNAI2 as mesenchymal markers have been implicated in aggressive behavior cancers." (PMID 40332096, 2025). "SNAI2 has been implicated in the diseases of melanocytes development and a variety of cancers." (PMID 37138850, 2023). "Together, our results indicated that SNAI2 might affect the development, prognosis, and therapy of cancers by associating with immune cells." (PMID 37251370, 2023). "Combined with our finding that SNAI2 was strongly related to the expression of CD276, NRP1, and CD44 in many cancer types, we speculated that the potential association between SNAI2 and CD276, CD44, or NRP1 was promising for our further studies." (PMID 37251370, 2023). "Higher than normal SNAI2 expression is associated with poorer prognosis, as observed in cases of pancreatic cancer, colorectal cancer and ovarian cancer, indicating its important role in cancer development and migration." (PMID 36980876, 2023). "The associations between SNAI2 and immune regulators in pan-cancer were displayed." (PMID 37251370, 2023). "SNAI2 plays an essential role in development and cancer-associated EMT." (PMID 30823890, 2019). "In addition, SNAI2 was associated with poor survival in most epithelial cancers through analyzing the pan-cancer Genomic Profiles." (PMID 29041931, 2017). "Moreover, we showed, in TCGA network of variant cancers and the ovarian microdissected profile, that SNAI2 was positively related with classical CAF activation markers, such as ACTA2, FAP, and PDGFRB." (PMID 29041931, 2017). "A Survival z-scores in different cancer types associated with the expression of SNAI2 mRNA." (PMID 29041931, 2017). "These Snai2-target genes could represent novel pharmacological targets and/or biomarkers in cancers linked to Snai2." (PMID 18182996, 2008). "Notably, upregulated SNAI2 has been previously implicated in the self-renewal of cancer stem cells." (PMID 35654777, 2022).
cancer (continued). "In conclusion, our study unravels a novel role of MEK1/2, HDACs, and SNAI2 in orchestrating survival of a specific class of cancers, driving the expression of two well-known mediators of apoptosis in aggressive cancers, BIM and BMF." (PMID 40560846, 2025). "SNAI2 (known as transrepressor SLUG) is a master regulator (together with SNAI1) in the epithelial-to-mesenchymal transition (EMT) of cancer cells." (PMID 39796763, 2025). "To gain insight into the HDACs that cooperate with SNAI2 TPM cancers, we tested the ability for SNAI2 overexpression to counteract inhibitors that selectively target subsets of HDACs." (PMID 40560846, 2025). "In TPM cancers, we observed that SNAI2 expression is elevated, suggesting a possible role in the aggressive phenotype of these cancers." (PMID 40560846, 2025). "With respect to the potential effect on transcriptional effects, we observed the most intense enrichment probability for SNAI2, which controls (among many other functions) cell stemness in the context of aging/cancer/metabolic dysfunction." (PMID 40136443, 2025). "SNAI2 has been demonstrated as a key target gene of FOSL1‐SEs to maintain cancer stemness and promote metastatic properties of HNSCC." (PMID 38032139, 2024). "Mechanistically, GNPNAT1 promoted cancer cell metastasis via repressing ubiquitination degradation of Snai2 in LUAD." (PMID 39062049, 2024). "In OvCA, lncRNA AC005224.4-mediated upregulation of SNAI2 elevated cancer cell invasion and migration by sponging miR-140-3p." (PMID 38584230, 2024). "Knockdown of PLK3 inhibited expression of MMP11 and SNAI2, known players in the regulation of cancer invasion and metastasis." (PMID 38169509, 2024). "The diminished methylation of the SNAI2 gene in tumors with histologic grade 3 proposes a novel role for this epithelial-mesenchymal transition (EMT) gene in cancer cell dedifferentiation." (PMID 38317965, 2024). "SNAI2 is irregularly expressed in several types of malignant cancers and plays a crucial role in cancer progression." (PMID 39221422, 2024). "JUN family and FOS family TFs have been reported to facilitate the EMT process by regulating E-cadherin, N-cadherin, and SNAI2 expression in cancers." (PMID 39732719, 2024). "A few studies showed the clue that stemness factors SOX2, BMI1, OCT4, or SOX9 can be regulated by ZEB1, SNAI1, or SNAI2, thereby promoting not only stemness and metastasis of cancer cells, but also resistance to radio- and chemotherapy." (PMID 39164745, 2024). "The relationship between the expression of four methyltransferase genes (DNMT1, (DNMT2, DNMT3A, DNMT3B) and SNAI2 in pan-cancer was investigated further." (PMID 37251370, 2023). "We then integrated ImmuneScore, EstimateScore, StromalScore, and neoantigens to further evaluate the relationship between SNAI2 expression and immune infiltration across cancers." (PMID 37251370, 2023). "Relative to SNAI1, regulatory machinery controlling the homeostasis levels of SNAI2 protein under EMT contexts in cancer especially HCC, is less known." (PMID 37596321, 2023). "Second, this study presents the role of SNAI2 in various cancers through bioinformatics analysis and is partially validated by clinical specimens from PAAD." (PMID 37251370, 2023). "We appraised the aberrant expression levels of SNAI2 in pan-cancer compared to human normal tissues, and further examined the upregulated SNAI2 protein and mRNA expression levels in clinical PAAD samples." (PMID 37251370, 2023). "In the majority of the 5 cancer types, PIK3CD expression was linked favorably with the expression of mesenchymal markers such as VIM (Vimentin), TWIST1, SNAI1 (SNAIL), SNAI2 (SLUG), and CDH2." (PMID 37861728, 2023). "According to the findings, the MMR genes were correlated with SNAI2, and this correlation was found in the majority of cancer types." (PMID 37251370, 2023).
cancer (continued). "These processes were most significantly enriched in high-SNAI2 cancer subgroups, but reverse results were found in ESCA, LAML, LUSC, SARC, and UCS." (PMID 37251370, 2023). "The Cancer Genome Atlas (TCGA), Genotype-Tissue Expression (GTEx), and Cancer Cell Line Encyclopedia (CCLE) databases were taken to examine the SNAI2 expression pattern in tissues and cancer cells." (PMID 37251370, 2023). "As one of main regulators during EMT and metastasis, SNAI2 is often upregulated in various cancer types; high SNAI2 expression normally predicts poor prognosis in cancer patients, including HCC." (PMID 37596321, 2023). "Another essential discovery of our study was that the expression of SNAI2 was highly related to immune infiltration in pan-cancer." (PMID 37251370, 2023). "Our results suggested that SNAI2 had the potential to predict the efficiency of ICIs in the corresponding cancers." (PMID 37251370, 2023). "According to the results, SNAI2 expression was positively correlated with the ImmuneScore, EstimateScore, and StromalScore in most cancers." (PMID 37251370, 2023). "As expected, the majority of HN279 cancer cells expressed MDK, together with a number of genes associated with the pre-nodal phenotype (eg SNAI2, AXL, STAT2) that were unaffected by ICB." (PMID 36973261, 2023). "In order to explore the mutation rate and mutation type of SNAI2 in different tumors, the genetic alteration of SNAI2 in various cancers from the TCGA cohorts was analyzed by the cBioPortal tool." (PMID 37251370, 2023). "It is interesting, in this regard, that TOX3 downregulation has been reported to facilitate epithelial-to-mesenchymal transition by repression of SNAI1 and SNAI2 in cancer cells." (PMID 36794750, 2023). "While SNAI2 also acted as a protective factor for some types of cancers including CESC, LUSC, PRAD, READ, THYM, and UVM." (PMID 37251370, 2023). "In this study, we conducted a systematic analysis of SNAI2 to demonstrate the different roles in various cancers." (PMID 37251370, 2023). "Overexpression of SNAI2 generated by stimulation TGF signaling gave cancer cells migratory and invasive characteristics." (PMID 37251370, 2023). "As reported in a previous study, activation of the Wnt/β-catenin signaling pathway enhanced SNAI2 expression in various cancers." (PMID 36674577, 2023). "SNAI2 was significantly correlated with immune-activated hallmarks, cancer immune cell infiltrations, and immunoregulators." (PMID 37251370, 2023). "The correlations between SNAI2 expression and immune cell infiltrations were analyzed to further elucidate the relationships between SNAI2 and cancer immunity." (PMID 37251370, 2023). "The heatmap data revealed a positive correlation between SNAI2 and the fourteen genes in the majority of detailed cancer types." (PMID 37251370, 2023). "And it is found that SNAI2 is a powerful pan-cancer prognostic biomarker, which can effectively predict immunotherapy response." (PMID 37251370, 2023). "We analyzed the correlation between SNAI2 levels and OS in 19 cancer types using Kaplan–Meier plotting." (PMID 34792282, 2022). "In the carcinogenesis process, SNAI2 has been reported to take active part in metastasis, progression, differentiation, and drug sensitivity in multiple cancer types." (PMID 36338978, 2022). "This corroborates previous findings linking their EMT-TF targets (ZEB1, SNAI1 and SNAI2) with cancer stem cells in CRC." (PMID 35565409, 2022). "SNAI2 is also indicated as a molecular determinant of cancer stem cell behavior and therapy resistance." (PMID 36230884, 2022). "Transcript levels of SNAI1 and SNAI2 were increased in most types of tumors when compared with non-cancer tissues." (PMID 35898399, 2022). "It was reported that low expression of SNAI2 was found in most PC tissue, but higher SNAI2 expression was detected only in the cancer cell clusters at the invasion/expansion front." (PMID 34792282, 2022).
cancer (continued). "The study identified FN1, CD44, TIMP1, SPARC and SNAI2 as common coding hub proteins for most of the drug-resistant cancer types." (PMID 35534592, 2022). "Wnt signaling is abnormally upregulated and directly stimulates the expression of SNAI1 and SNAI2 in various cancers." (PMID 35144601, 2022). "Aberrant SNAI2 expression has been observed in various cancer types and possibly predicts poor prognosis in cancer patients." (PMID 34792282, 2022). "One molecular pathway responsible for the mesenchymal phenotype in this cancer is the expression of SNAI2, driven by KRAS, a RAS oncogene family member." (PMID 36669020, 2022). "More interestingly, miR-1 was previously found to post-transcriptionally regulate SNAI2 to inhibit EMT in different cancer types." (PMID 34510400, 2021). "CSCs were characterized by the expression of the stem cell markers TWIST, the epithelial cell adhesion molecule (EPCAM), the transcription factors SNAI1 (SNAIL) and SNAI2 (SLUG) and cancer markers such as CD44 and prominin-1 (CD133)." (PMID 34445612, 2021). "YAP1 contributes to cancer invasion and migration by promoting SNAI2 transcription through the transcription cofactor TEAD, in vivo and in vitro assays." (PMID 34446793, 2021). "For example, many of the cancer cells in HNSCC express SNAI2, while only few of those cells express a full pEMT program that includes TGFBI, SERPINE1 and other ESGs, but not higher SNAI2 levels." (PMID 33972543, 2021). "Analysis of SNAI2 expression in a different cohort of approximately 2000 pediatric cancers from the St." (PMID 33420019, 2021). "The induction of EMT by SNAI2 can not only promote the invasion ability in cancer cells, but also lead to drug resistance, pressure, and immune response." (PMID 32788880, 2020). "We performed qPCR analysis of SNAI2, miR-222-3p and PDCD10 expression levels in 38 specimens of EOC patients collected from Hunan Cancer Hospital, and observed a strong correlation between SNAI2 and PDCD10 expression levels." (PMID 32483426, 2020). "SNAI2, a member of the snail zinc finger protein family, plays an important role in the metastasis of several types of carcinoma." (PMID 31749661, 2019). "Discovery of SNAI2-induced EMT in bladder carcinoma cell line reaffirms that EMT promote metastasis in carcinoma through dissolution of desmosomes and remodeling of cytoskeletal proteins." (PMID 31558913, 2019). "In fact, recent works have questioned the importance of EMT in metastasis formation, also proposing a negligible role of Snai2 in cancer cell metastatic properties." (PMID 29674627, 2018). "Meanwhile, SNAI2 knockdown in PCa suppresses the activity of cancer stem cells by reducing the expression of multiple pluripotent genes." (PMID 29552304, 2018). "Several studies have also showed that the miR-203/SNAI2 axis plays a broad-spectrum role in various types of cancers." (PMID 29552304, 2018). "EMT is a process frequently associated with cancer and it involves multiple regulators, including SNAI1, SNAI2, TWIST1 and ZEB1 as well as their targets." (PMID 30379847, 2018). "It is generally accepted that the SLUG (SNAI2) transcription factor, encoded by the SNAI2 gene, induces EMT, initiating cancer dissemination processes." (PMID 30189837, 2018). "SNAI2 expression was evaluated in microdissected profiles of various cancers and in various molecular subtypes of OC." (PMID 29041931, 2017). "SNAI2 amplification or interaction with specific oncogenes has been demonstrated in a wide spectrum of human cancers." (PMID 29041931, 2017). "SLUG (also known as Snai2) is a zinc-finger transcription factor correlated with poor outcomes in various cancers." (PMID 27823965, 2017).
cancer (continued). "Intense nuclear and faint cytoplasmic SNAI2 expression was detected in carcinoma and stromal cells of human OC." (PMID 29041931, 2017). "Next, we found that SNAI2 in the carcinoma cells exerted a negligible effect in discriminating the patients’ overall survival (OS) (median survival 23.4 vs 30.9 months, p = 0.46)." (PMID 29041931, 2017). "SNAI1 and SNAI2 are two of the most important transcription factors that regulate EMT and they have also been implicated in cancer progression." (PMID 26771648, 2016). "Although SNAI2 is regarded as a cancer promoter factor based on the facts that SNAI2 promotes survival, suppresses apoptosis and drives EMT transition and metastasis in many types of cancer." (PMID 27760172, 2016). "We note that known EMT drivers ZEB1, SNAI2, and TCF4 in module 5 have significant associations with survival in our pan-cancer analysis (p values 8.5 × 10–6, 5.3 × 10–4, 1.3 × 10–3 and rankings 153, 749, and 1098, respectively, out of 11,119 total genes)." (PMID 27287041, 2016). "To exploit the roles of endogenous SNAI2 in HCC cells, we demonstrate herein that knockdown of SNAI2 expression with shRNA lentivirus lead to enhanced anchorage-independent growth and up-regulated cancer stem cell gene expression in HCC cells." (PMID 27760172, 2016). "In agreement with this, a recent report showed that reduced expression of SNAI2 reduces the aggressiveness of cancer cells." (PMID 27528030, 2016). "In mammary epithelial cells, SNAI2 is enriched in EpCAM-expressing cells while in some of the pulmonary metastatic high-grade carcinomas, the expression of epithelial marker EpCAM is downregulated and so does the SNAI2 expression." (PMID 27760172, 2016). "Recent independent studies have shown that overexpression of SNAI2 alters cell invasion, motility, chemoresistance, metastasis and poor prognosis in several human cancers." (PMID 25871397, 2015). "To do so, we compared Pol II pausing signal and expression levels on SNAI1, CDH1 and SNAI2 genes in several cancer cell lines grown in steady-state conditions in the absence of activation." (PMID 25820424, 2015). "Consistent with its function in neural crest development, SNAI2 is an important driver of cancer progression." (PMID 25797249, 2015). "Numerous inducers of EMT in cancer cells have been identified including transforming growth factor-β, Wnt/β-catenin, Snail/SNAI2, Twist and talin." (PMID 25871397, 2015). "Genes associated with the actions of miR-203 in other cancers, such as BIRC5, SNAI2, P63, and c-Jun, were not enriched in our samples." (PMID 25284788, 2014). "The receptor tyrosine kinase Axl is implicated in the Snai1-, Snai2-, IL6-, and STAT3-mediated activation of EMT as well as the metastasis promoting AKT/NF-κB and AKT/Snai2 pathways in multiple cancer types." (PMID 25566507, 2014). "Among the genes upregulated in GFPHigh cells are cytokines (IL-6, IL-8, or TNF) and transcription factors (KLF6, ATF3, SNAI2) that have been previously related with cancer stemness, cellular plasticity, or both." (PMID 25414831, 2014). "While the SNAI1 and SNAI2 genes are reported to be frequently reactivated in numerous carcinomas (breast, esophageal, colon, kidney), the status of the related SNAI3 gene has remained unclear." (PMID 24638100, 2014). "More relevantly, both Snai1 and Snai2 have exhibited migratory and anti-apoptotic functions when studied in cancer models." (PMID 23874916, 2013). "SNAI1 and SNAI2 are transcription factors that initiate Epithelial-to-Mesenchymal cell transitions throughout development and in cancer metastasis." (PMID 20046880, 2009). "Collectively, this study provides novel insight into the potential role of SNAI1 and SNAI2 in development and cancer metastasis." (PMID 20046880, 2009). "Uncommitted progenitor cells express Snai2 and aberrant activation of Snai2 pathways is key in the development of cancers derived from many tissues." (PMID 18182996, 2008).